RN7SKP85 (RN7SK pseudogene 85)
Gene: Miscellaneous RNA gene on chromosome 8 (98,921,233 to 98,921,550, reverse strand). Ensembl gene ENSG00000223281.
Homologues: Orthologues: chimpanzee 7SK (99% identical). Paralogues in human: RN7SKP176 (73% identical), RN7SKP203 (73% identical), RN7SKP180 (72% identical), RN7SKP243 (72% identical), RN7SKP133 (70% identical), RN7SKP255 (70% identical), RN7SKP200 (70% identical), RN7SKP213 (70% identical), RN7SKP296 (70% identical), RN7SKP47 (70% identical), RN7SKP50 (70% identical), RN7SKP217 (70% identical), and 283 more.